YTHDF1 (YTH N6-methyladenosine RNA binding protein F1)
Diseases named in the same sentence as YTHDF1 in open-access papers (continued):
Sharing a sentence is not in itself a finding about the gene and the disease.
colorectal cancer (74 papers, 2018 to 2025). A primary or metastatic malignant neoplasm that affects the colon or rectum. "The ectopic expression of ARHGEF2 restores the impaired metastatic ability caused by the loss of YTHDF1 in colorectal cancer." (PMID 40986143, 2025). "Previous studies have shown that YTHDF1 is linked to the progression of various cancers, including non-small cell lung cancer, colorectal carcinoma, and ovarian cancer." (PMID 38491196, 2024). "High YTHDF1 level is significantly associated with metastatic gene signature in colorectal cancer, while YTHDF1-knockout mice inhibited tumor growth in vivo." (PMID 36347025, 2022). "With respect to 'readers', both YTHDF1 and YTHDC1 were linked to higher GS, pathological T and pathological N. YTHDF1 is overexpressed in the colorectal cancer (CRC), and inhibition of Wnt/β-catenin pathway can be achieved by YTHDF1 silencing in CRC cells." (PMID 33995635, 2021). "In colorectal cancer, the reader YTHDF1 was found to be overexpressed and associated with the stem-like features of cancer cells." (PMID 34149792, 2021). "Another study also showed that oncogene c-Myc promotes YTHDF1 expression in colorectal cancer, whose high expression was associated with poorer overall survival." (PMID 31653849, 2019). "Interestingly, YTHDF1 is implicated in the development of colorectal carcinomas, and its expression has been shown to be significantly augmented in this type of cancer." (PMID 34968289, 2020). "Moreover, it has been stated that overexpression of YTHDF1 (m6A binding protein, reader) in colorectal cancer is associated with poorer overall survival, and that knockdown of YTHDF1 in vitro sensitizes cells to anticancer drugs." (PMID 31320814, 2019). "Specifically, high METTL3 and YTHDF1 expression is detected in neoplastic tissues from colorectal cancer patients with pulmonary metastases." (PMID 40986143, 2025). "YTHDF1 serves an oncogenic role in colorectal cancer (CRC) through binding to m 6A sites of Rho guanine nucleotide exchange factor 2 (ARHGEF2) mRNA and promoting the translation of ARHGEF2." (PMID 40483535, 2025). "The study revealed high expression of METTL3 and YTHDF1 in the tumors of patients with pulmonary metastasis of colorectal cancer." (PMID 38605400, 2024). "Targeting regulators such as METTL3, METTL14, IGF2BP3, or YTHDF1 can alleviate T-cell suppression in melanoma, colorectal cancer, non-small cell lung cancer (NSCLC), and breast cancer." (PMID 39372415, 2024). "YTHDF1 is significantly associated with metastatic gene signatures through ARHGEF2 translation and RhoA signaling activation in colorectal cancer." (PMID 39185313, 2024). "To further explore this mechanism, we conducted experiments with si-YTHDF1 in colorectal cancer cell lines." (PMID 38605400, 2024). "YTHDF1 facilitated cell proliferation in colorectal cancer cell lines and primary organoids, as well as lung and liver metastasis in vivo." (PMID 39582531, 2024). "Targeting YTHDF1 in colorectal cancer can relieve the inhibition of CD8+ T cells and enhance the efficacy of anti-PD-1." (PMID 39372415, 2024). "A recent study has reported that silence c-Myc inhibited YTHDF1 expression, resulting in the suppression of colorectal cancer proliferation and the sensitization to the exposure of anticancer drugs, such as 5-FU and oxaliplatin." (PMID 37152066, 2023). "In colorectal cancer, the oncogenic transcription factor c-Myc promotes the expression of YTHDF1 and plays a significant role in colorectal cancer progression." (PMID 36650570, 2023). "As expected, the YTHDF1-WT–rescued cells produced much larger tumors than the AFA mutants, suggesting that YTHDF1 O-GlcNAcylation promotes colorectal cancer, probably via c-Myc." (PMID 37086786, 2023). "In colorectal cancer, YTHDF1 plays an important oncogenic role in cellular self-renewal and differentiation through the Wnt/β-catenin pathway." (PMID 36733344, 2023).
colorectal cancer (continued). "YTHDF1 was obviously increased in cisplatin-resistant colorectal cancer cells, which was interacting at 3’ UTR of GLS1, and promoting the translation of GLS1 to induce cisplatin resistance." (PMID 36707507, 2023). "Database analysis revealed the expressions of VEGFA, CCND1, and YTHDF1 were all upregulated in colorectal cancer tissues compared with the normal cohort." (PMID 38001065, 2023). "YTHDF1 was also related to the progression of cervical cancer, non-small cell lung cancer, colorectal cancer, and gastric carcinogenesis." (PMID 36072430, 2022). "Another interesting finding is that YTHDF1 can promote cisplatin resistance by reprogramming GLS1-glutamine metabolism in colorectal cancer." (PMID 35794625, 2022). "In another study, researchers found that YTHDF1 promotes tumor development by maintaining the stemness of tumor cells in colorectal cancer." (PMID 36411870, 2022). "Deletion of YTHDF1 gene inhibits the Wnt/β-catenin signaling pathway, thus reducing the tumorigenicity of colorectal cancer cells." (PMID 34103054, 2021). "Mechanistically, one study noticed that downregulated expression of YTHDF1 remarkably suppressed the tumorigenicity in colorectal cancer cells and xenograft growth in mice via the WNT/β-catenin pathway, which indicates an oncogenic role of YTHDF1 in CRC." (PMID 34381710, 2021). "YTHDF1 was reported to be overexpressed in ovarian cancer, colorectal cancer, and breast cancer and facilitate tumorigenesis and metastasis." (PMID 34589481, 2021). "In colorectal cancer, the prognostic value of the m6A RNA methylation regulators YTHDF1 and HNRNPC has been described." (PMID 34149792, 2021). "In colorectal cancer, YTHDF1 plays a vital oncogenic role in cell self-renewal and differentiation via the Wnt/β-catenin pathway." (PMID 34026603, 2021). "In colorectal cancer, YTHDF1 is regarded as an oncogene; In breast cancer, overexpression of YTHDF1 predicts worse survival." (PMID 34026603, 2021). "Low expression of YTHDF1 was found to be correlated with the infiltration of CD8+ T cells in colorectal carcinoma (CRC) tissue." (PMID 33692959, 2021). "For instance, high YTHDF1 expression was a significant predictor of malignant tumor behaviors and poor prognosis in colorectal cancer." (PMID 32984346, 2020). "In colorectal cancer, knockout of YTHDF1 can suppress the proliferation of cancer cells and enhance their sensitivity to chemotherapy drugs such as 5-FU and oxaliplatin." (PMID 33072775, 2020). "In colorectal cancer tissues, c-Myc drives the expression of YTHDF1 transcriptionally, and high level of YTHDF1 suggests poor prognosis in patients." (PMID 31921664, 2019). "YTHDF1 is overexpressed in colorectal cancer, and YTHDF1 knockdown significantly inhibits Wnt/β-catenin pathway activity in colorectal cancer cells." (PMID 31808521, 2019). "Given that clinical sequence data in colorectal cancer indicate that overexpression of YTHDF1 is outstanding among other family members, we studied the role of Ythdf1 and the transcriptional control of YTHDF1." (PMID 29484125, 2018). "YTHDF1 is up-regulated in colorectal cancer and ovarian cancer." (PMID 40483535, 2025). "Additionally, through WB and IHC experiments, we further confirmed the high expression of METTL3 and YTHDF1 in colorectal cancer lung metastases." (PMID 38605400, 2024). "Additionally, through sequencing and clinical sample testing, we observed elevated expression levels of METTL3 and YTHDF1 in samples of colorectal cancer lung metastasis." (PMID 38605400, 2024). "Moreover, YTHDF1 overexpression holds clinical diagnostic significance across various cancers, including NSCLC, breast cancer, cervical cancer, GC, and colorectal cancer." (PMID 39185313, 2024). "Then, the role of YTHDF1 in colorectal cancer cells was investigated." (PMID 38001065, 2023).
colorectal cancer (continued). "We first carried out The Cancer Genome Atlas analysis and found that in colon adenocarcinoma and rectal adenocarcinoma samples, both YTHDF1 and c-Myc are overexpressed in the tumor samples, indicative of a positive correlation between YTHDF1 and c-Myc in colorectal cancer." (PMID 37086786, 2023). "However, in colorectal cancer, YTHDF1 is significantly up-regulated, which reduces the sensitivity to cisplatin." (PMID 35022030, 2022). "Thus, YTHDF1 promotes cisplatin resistance through reprogramming GLS1-glutamine metabolism in colorectal cancer." (PMID 35022030, 2022). "Conversely, YTHDF1 gene expression is reported to be significantly upregulated in colorectal cancer, thereby reducing the sensitivity of tumor cells to cisplatin, suggesting that YTHDF1 mediates chemoresistance through distinct expression patterns in different cancer types." (PMID 35794625, 2022). "c-Myc promoted the expression of YTHDF1 in colorectal carcinoma." (PMID 35197112, 2022). "In colorectal cancer, upregulated YTHDF1 could stabilize transcripts of the oncogene C-MYC and then promote tumor cell proliferation." (PMID 33758623, 2021). "It is reported that the expression of YTHDF1 is significantly increased in colorectal cancer." (PMID 34103054, 2021). "In addition, YTHDF1 knockout in mice with colorectal cancer was found to lead to tumor shrinkage and prolonged survival." (PMID 34359836, 2021). "Furthermore, knockdown of YTHDF1 inhibits colorectal cancer cell proliferation, colonosphere formation, anti-cancer drug sensitivity and murine xenograft tumor growth in mice." (PMID 33372610, 2020). "Additionally, the m6A reader YTHDF1 was also found to be upregulated in colorectal cancer and correlated with poor prognosis of patients." (PMID 33372610, 2020). "This study, aimed to explore the role of YTHDF1 in the colorectal cancer (CRC)." (PMID 31131257, 2019). "Previously, YTHDF1 was elucidated to be an oncogene in colorectal cancer." (PMID 31632489, 2019). "Moreover, YTHDF1 was found to be highly expressed in colorectal cancer and the knockdown of YTHDF1 could significantly suppress the tumor growth both in vitro and in vivo." (PMID 33240891, 2020). "YTHDF1 suppresses antitumor immune responses via the m6A–p65–CXCL1/CXCR2 axis, driving colorectal cancer progression and representing a potential therapeutic target for immune checkpoint inhibitor therapy." (PMID 40986143, 2025). "It is reported that YTHDF1 was overexpressed in different cancers, including NSCLC, breast cancers, cervical, gastric and colorectal cancers." (PMID 36707507, 2023). "In colorectal cancer (CRC) cells, YTHDF1 induced cisplatin resistance by regulating glutamine metabolism through glutaminase." (PMID 35197112, 2022). "Consistently, a recent study reported that YTHDF1 regulates CRC tumorigenesis and metastasis by promoting ARHGEF2 translation and RhoA signaling in colorectal cancer." (PMID 36347025, 2022). "The results showed that YTHDF1 had significantly higher expression in most cancer types except lymphoma and THCA, which was consistent with previous studies in lung and colorectal cancer." (PMID 34026603, 2021). "Two SNPs rs2024768 and rs6090289 in the YTHDF1 gene could not modify the risk of colorectal cancer." (PMID 34151473, 2021). "To validate the roles of YTHDF1 in immune response downregulation in vivo, we established mouse xenograft models with murine colorectal cancer MC38 cells because mouse syngeneic models for GC were not available." (PMID 39587835, 2025). "In addition, YTHDF1 escalates the translation of ARHGEF2, activating RhoA signaling, thereby driving tumorigenesis and metastasis in colorectal cancer." (PMID 40251202, 2025). "Similarly, YTHDF1 promotes ARHGEF2 translation in an m6A-dependent manner and promotes progression of colorectal cancer through RhoA signaling." (PMID 37259333, 2023).
colorectal cancer (continued). "Meanwhile, it is required for WNT-driven intestinal stem cell regeneration and intestinal tumor development, as YTHDF1 can facilitate the translation of TCF7L2/TCF4, the major transcriptional effector for β-catenin in mouse intestine and human colorectal cancer cells." (PMID 37152066, 2023). "YTHDF1 also enhances the transcriptional efficiency of ANKLE1 however it does not maintain ANKLE1 mRNA stability, via recognition of 6A modification thus acting as a tumor suppressor and playing a crucial role in the inhibition of colorectal cancer cell proliferation." (PMID 36650570, 2023). "However, whether the up-regulation of YTHDF1 and YTHDF2 is effective for patients with colorectal cancer needs further research." (PMID 35069586, 2021).
ovarian carcinoma (62 papers, 2020 to 2025). A malignant neoplasm originating from the surface ovarian epithelium. "The expression of YTHDF1, which is an m6A modification reader, is also associated with ovarian cancer progression." (PMID 35251990, 2022). "Previous studies showed that the reader protein YTHDF1 associates with the progression of various cancers, including non-small cell lung cancer, and ovarian cancer." (PMID 35524932, 2022). "Up-regulation of YTHDF1 is associated with the poor prognosis of ovarian cancer patients and knockdown of YTHDF1 can inhibit the stem cell-like features of cisplatin-resistant ovarian cancer cells." (PMID 33928028, 2021). "In the case of ovarian cancer, YTHDF1 was also found to be overexpressed and associated with poor clinical outcome." (PMID 34497675, 2021). "YTHDF1 is frequently overexpressed in ovarian cancer and up-regulation of YTHDF1 is associated with the adverse prognosis of ovarian cancer patients." (PMID 33928028, 2021). "Meanwhile, high expression of YTHDF1 was associated with poor prognosis of ovarian cancer." (PMID 36894952, 2023). "The up regulation of YTHDF1 is detected in ovarian cancer and associated with adverse prognosis." (PMID 34151473, 2021). "In addition, the overexpression of YTHDF1 in ovarian cancer patients is associated with poor prognosis, thus poor prognosis for patients with high YTHDF1 expression." (PMID 34794452, 2021). "Moreover, overexpression of YTHDF1 was associated with poor prognosis of ovarian cancer." (PMID 36439881, 2022). "The mammalian homolog YTHDF1 stimulates translation directly and indirectly via stimulation of eIF3C translation, and amplification of YTHDF1 stimulates proliferation in ovarian cancer." (PMID 41322074, 2025). "For example, YTHDF1, a typical m6A reader, was reported to promote the development of ovarian cancer." (PMID 40069867, 2025). "In ovarian cancer, the m6A readers YTHDF1 and YTHDF2 specifically recognize RNA transcripts with m6A modification and affect their translation and decay, respectively." (PMID 38424195, 2024). "Mechanisms research indicated that YTHDF1 promotes the CSC-like characteristics of the cisplatin-resistant ovarian cancer cells via recognition of m6A-edited TRIM29 and increased TRIM29 translation." (PMID 36650570, 2023). "YTHDF1 also confers cisplatin-resistant ovarian cancer cells with CSC-like traits by promoting m6A-TRIM29 mRNA translation." (PMID 36999016, 2023). "The abnormal expression of m6A-related regulatory enzymes including METTL3, FTO, ALKBH5, IGF2BP1, YTHDF1, and YTHDF2 is closely linked with the growth, metastasis, invasion, and chemotherapy resistance in ovarian cancer." (PMID 37781028, 2023). "YTHDF1 promotes ovarian cancer tumorigenesis and metastasis by binding to m6A-modified eIF3c mRNA and enhancing eIF3c translation in a m6A-dependent manner while promoting overall translational output." (PMID 36360287, 2022). "YTHDF1 promoted the eIF3C translation in ovarian cancer, thus promoting the development and metastasis of ovarian cancer." (PMID 35197112, 2022). "In ovarian cancer, YTH domain-containing family protein 1 (YTHDF1) promotes the translation of eukaryotic translation initiation factor 3 subunit C to promote tumorigenesis and metastasis." (PMID 36581942, 2022). "The m6A reader YTHDF1 was proved to promote ovarian cancer progression via augmenting EIF3C translation." (PMID 36072430, 2022). "YTHDF1 affected EIF3C translation in an m6A-dependent manner to promote ovarian cancer progression and metastasis." (PMID 36439881, 2022). "In ovarian cancer, YTHDF1 facilitates tumorigenesis and metastasis by promoting the translation of EIF3C mRNA in an m6A-dependent manner." (PMID 35806168, 2022). "YTHDF1 accelerated the growth and metastasis of ovarian cancer in vivo and in vitro by promoting the m6A-modified translation of EIF3C." (PMID 34497675, 2021).